MIR517B (microRNA 517b)
Synonyms: hsa-mir-517b; MIRN517B; mir-517b
Gene: MicroRNA gene on chromosome 19 (53,721,076 to 53,721,142, forward strand). Ensembl gene ENSG00000207837.
Gene Ontology:
Biological process: miRNA-mediated post-transcriptional gene silencing
Homologues: Orthologues: chimpanzee MIR517B-1 (100% identical). Paralogues in human: MIR517A (99% identical), MIR519B (88% identical), MIR523 (88% identical), MIR518E (87% identical), MIR519A2 (87% identical), MIR519C (87% identical), MIR521-1 (87% identical), MIR522 (87% identical), MIR516A1 (85% identical), MIR516A2 (85% identical), MIR518C (85% identical), MIR518D (85% identical), and 12 more.